ARG1 (arginase 1)
Diseases named in the same sentence as ARG1 in open-access papers (continued):
Sharing a sentence is not in itself a finding about the gene and the disease.
infection (continued). "Because Arg-1 is only moderately expressed in T. cruzi-infected wildtype mice, we elucidated the role of Arg-1 and AAM during infection in IL-13-overexpressing (IL-13tg) mice, which are characterized by an inflammation-induced development of AAM and an accompanied elevated expression of Arg-1." (PMID 30555475, 2018). "In the liver on day 7 post-infection, the expression of iNOS, IL-1β, IL-6, IL-12 p40, TNF-α, IL-10, TGF-β, CCR2, CCL2, IFN-γ and IL-4 was significantly up-regulated, and the expression of Arg-1 was down-regulated in both of MRP14-KO mice and WT mice." (PMID 29902248, 2018). "The level of the Arg1 transcript was increased in cells transfected with the let-7e inhibitor 24 h after infection (35%), but the percentage of cells expressing ARG1 and mean intensity of ARG1 were not noticeably modified." (PMID 30555476, 2018). "The absence of TLR2 and inhibition of let-7e increased the expression of the arginase 1 (Arg1) mRNA but did not alter the protein level during infection." (PMID 30555476, 2018). "Notably, Arg1 expression levels at 24 h after in vitro RH and ME49 infection were increased by 2.0 ± 0.3- and 2.9 ± 0.1-fold, respectively, as compared to control (*p < 0.05)." (PMID 29459868, 2018). "This is a characteristic of infection immunity in infection with T. gondii in the central nervous system, and SOCS1, a negative regulator of toxoplasmic encephalitis, may play a role in the increase in Arg1 levels to suppress NO production." (PMID 29459868, 2018). "Moreover, Arg1 expression was higher in ME49 infection than in RH infection, whereas nitrite production was lower in ME49 infection than in RH infection." (PMID 29459868, 2018). "The fact that Arg-1 and NOS2 coexist in the here examined T. cruzi-infected IL-13tg mice may favor a role of MDSC in the outcome of infection." (PMID 30555475, 2018). "It was shown that during H37Rv infection, M1-type markers, phosphorylated STAT1 and iNOS, and M2-type markers, phosphorylated STAT6 and Arg-1, were increased in varying degree, indicating that M. tb infection induced both M1- and M2-type polarization of macrophages." (PMID 28835201, 2017). "Although the infection upregulated the gene expression of markers expressed on alternatively activated macrophages (Arg1 and Chi3l3), Ebi3 did not have any impact on their expression in the heart of 15-day-infected animals." (PMID 29033934, 2017). "The increase in L-arginine uptake and ARG1 activity induces polyamines production, which correlates with the increase of IL-10 and reduction of IL-12 and TNF-α levels in L. donovani THP-1-derived macrophages infection." (PMID 29379478, 2017). "Having shown that in the absence of macrophage SOCS3 Mtb evades in early appearing Arg1-expressing cells, we next analyzed the fate of mycobacteria in different types of macrophages during the course of infection in vivo." (PMID 29176982, 2017). "However, high Arg1 expression preceded the increased induction of NOS2 and at early time points of infection mycobacteria were mostly found in cells positive for Arg1." (PMID 29176982, 2017). "The suppression of Arg1 expression by type I IFN, and indeed of other genes associated with alternatively activated macrophages, was also observed during in vivo infection in the absence of IFN-γ signaling." (PMID 27849167, 2016). "In addition, the differential expression of ARG1 in lungs of rabbits infected by Mtb CDC 1551 and HN878 can be a contributing factor to the different infection outcome by the two strains." (PMID 27148269, 2016). "At 16 h post-infection (approximately the time needed for the differentiation of promastigotes to the amastigote form), significant induction of Arg1 was observed for the IMT-151 strain, but not the others." (PMID 26684322, 2015).
infection (continued). "In total, these data suggest that although myeloid cell Arg1 inhibits the antiviral T cell response, this is not through the suppression of total T cell numbers at immune inductive sites or the sites of infection and inflammation." (PMID 26436766, 2015). "As early as 24 hours post infection, infected peritoneal elicited macrophages show properties of anti-inflammatory, alternatively-activated/M2 polarization resulting in increased expression of the M2 markers: mannose receptor (CD206), Fizz-1, Arg-1 and Ym1." (PMID 23349802, 2013). "In addition to Arg1, FIZZ-1 was significantly increased in the lungs of LVS infected mice compared to mock infected controls at each time point after infection." (PMID 24324751, 2013). "Levels of Thbs1 and Arg1 in uninfected BMMΦ were comparable to the ones in BMMΦ after 1 h infection (data not shown)." (PMID 23922979, 2013). "Collectively these data indicate that L. donovani infection induces macrophage STAT6 activation and STAT6-dependent arg1 expression, which do not require but are amplified by type 2 cytokines, and which contribute to impaired control of infection." (PMID 22275864, 2012). "Third we found that at the site of visceral infection (spleen) in hamsters there is dominant expression of arg1, such that the arg1 to NOS2 ratio in hamsters with progressive disease was thousands-fold greater than the ratio observed in mice, which are able to control the infection." (PMID 22275864, 2012). "Arginase-1 expression was significantly increased in MyD88 KO mice at day 14 following infection but not earlier." (PMID 22879997, 2012). "Whilst iNOS expression in the skin infected by the complemented ΔaaaA mutant mirrored that in PAO1 8 days post infection, Arg1 expression did not." (PMID 22927813, 2012). "Infection of STAT6−/− MØ with all three strains failed to induce arginase-1 protein, in contrast to infection of MØ from STAT6+/+ littermates in which we detected ROP16-dependent arginase-1 induction." (PMID 21931552, 2011). "ΔROP16 tachyzoites that failed to induce host cell arginase-1 displayed increased replication and dissemination during in vivo infection." (PMID 21931552, 2011). "Of note, at 48 hours after infection, a low level of Arg1 was noted (data not shown) in the lungs of Klebsiella-infected mice which disappeared after 4 days (as shown)." (PMID 21246055, 2011). "We also found no role for AAMs and Arg1 in infection-induced pathology in the response to T. muris in either chronic (Th1 dominated) or acute (Th2 dominated) infections." (PMID 21585399, 2011). "In contrast, the M2 markers found in inflammatory zone 1 (FIZZ1) and arginase-1 were not differentially expressed in the stomach at four, eight or 26 weeks of infection compared to naïve mice." (PMID 21124899, 2010). "During Th1 responses, CAM-derived Arg1 antagonizes NOS2 activity, which promotes infection by intracellular pathogens, while in Th2 responses Arg1-expressing AAMs contribute to the resolution of chronic Th2-driven inflammation and fibrosis by functioning as suppressor cells." (PMID 19360123, 2009). "Additionally, the expression of MyD88, NF-κB p65, iNOS, and Arg-1 was significantly elevated in the E. granulosus group, confirming that GHSR-/- mice exhibited milder infection and a lower inflammatory status, further supporting the conclusion that GHSR deficiency alleviates E. granulosus infection." (PMID 40065480, 2025). "During infection, these AAMacs have been found to highly express a variety of immunoregulatory and wound healing molecules including chitinase-like proteins that have lost their enzymatic activities e.g., Chil3, resistin-like molecules including RELM- α, and Arg1." (PMID 40501701, 2025). "Furthermore, after infection and the addition of a PKA activator, the expression levels of p-CREB (P < 0.05), C/EBPβ (P < 0.05), Arg-1 (P < 0.01), and IL-10 (P < 0.05) were significantly upregulated in human dMφ compared with those of the group infected with T. gondii alone." (PMID 39994736, 2025).
infection (continued). "Regarding Arg-1 activity, our data demonstrated the induction of arginase activity in AAMΦ increased by almost twice when they were infected with the QRO isolate, while infection with the CI2 isolate resulted in arginase activity similar to that observed in uninfected AAMΦ." (PMID 39452749, 2024). "Moreover, lung PD-L1+ neutrophils produced high amounts of Arg-1 during the course of infection, while PD-L1− neutrophils failed to do so." (PMID 39392875, 2024). "Furthermore, expression of Arg1 mRNA, which represents M2 macrophage polarization, did not increase with longer infection duration in Trem2−/− mice." (PMID 37430471, 2023). "Thus, the deletion of ARG1 in macrophages neither resulted in a better infection control of intracellular Salmonella nor in an altered expression of important host immune response genes in vitro." (PMID 34359992, 2021). "MDSCs have been shown to suppress T-cell responses in several infection and non-infection models of inflammation, and their suppressive activity has been assigned to various factors including nitric oxide (NO), arginase-1, reactive oxygen species and peroxynitrite." (PMID 32269573, 2020). "Additionally, RHΔrop16 strain infection significantly promoted M1 macrophage phenotypes of CD80 and CD86, and decreased CD206 expression of M2 macrophages, with upregulation of the iNOS and downregulation of the Arg-1 expression in placental homogenates." (PMID 32082272, 2019). "In addition, L. major infection induces NOS2 expression by activating TLR4, although ARG1 expression is independent of TLR4 during infection in vivo and in vitro." (PMID 30555476, 2018). "Inhibition of Arg1 during super-infection increased bacterial burden in Stat2−/−, but not WT mice." (PMID 30337919, 2018). "Infection with N. americanus may not affect the levels of IL-4 and arginase-1 (Arg-1) expression by the M2 macrophages, although it results inhigher numbers of CD206+CD23+IL-10+ monocytes." (PMID 30274434, 2018). "Beside these common markers, some genes were modulated in animals acutely infected by specific strains: Tnf was downregulated by X10 infection, Nos2 for X10 and VFRA, Arg1 for Esm and 10R, while infection with CM17 and Sc43 strains did not lead to modulation of Tgfb1 gene expression." (PMID 28827716, 2017). "However, viral loads in the muscle tissue of T cell-depleted WT and LysMcre;Arg1F/F mice at 14 dpi were not significantly different, suggesting that Arg1 activity in macrophages inhibited the antiviral activity of T cells at the sites of infection." (PMID 26436766, 2015). "Furthermore, specific markers for M2 such as arginase-1, mannose receptor (CD206) and FIZZ1 (found in areas of inflammation) were up-regulated significantly in full thickness sections of intestinal tissue during infection, when compared to controls." (PMID 24465430, 2014). "Similar to LCMV C13 infection, it was recently demonstrated that infection of mice with the arthritogenic alphaviruses Ross River virus (RRV) and chikungunya virus (CHIKV) resulted in the induction of Arg1 in macrophages in the infected and inflamed musculoskeletal tissues." (PMID 25250029, 2014). "Thus, induction of Arg1 by LVS infection was independent of triggering alternative activation in the host." (PMID 24324751, 2013). "Indeed, following infection with the intracellular parasite L. mexicana we demonstrated that it was changes in Arginase-1 and iNOS rather than changes in kinase mediated signalling that dictated the subsequent in vivo response to MKP-2 deletion." (PMID 23437409, 2013). "LysMcreIL-4Rα-/lox mice which lack IL-4/IL-13 induced alternative activation of macrophages were found to have increased resistance to infection, while neutralization of endogenous arginase 1 with N-hydroxy-nor-L-arginine leads to complete healing in BALB/c mice." (PMID 24204259, 2013). "Similarly, we detected induction of arginase-1 by immunofluorescence assay during RH but not ΔROP16 infection (respectively)." (PMID 21931552, 2011).
infection (continued). "How Arg1 might contribute to the suppressive functions of AAMs at early or late time points after infection is currently not understood." (PMID 21246055, 2011). "Fungus-induced Arg1 expression in alveolar macrophages was also rapidly induced as early as 6 hours after infection and at none of the time points tested did we detect appreciable NOS2 expression unlike in mice infected with K. pneumoniae that showed brisk NOS2 expression." (PMID 21246055, 2011). "To exclude that the unaltered bacterial burden in ARG1-gene-deficient or pharmacologically blocked mice is due to a non-functional NRAMP1, we investigated in vitro whether the presence or absence of functional NRAMP1 has an impact on the role of ARG1 during infection of macrophages with S.tm." (PMID 34359992, 2021). "However, while the NOS2/Arg1 expression ratio remained constantly elevated in DCs isolated from H99γ infected mice at all time points, the CXCL9/FIZZ1 expression ratio peaks at day 7 post-inoculation and declines by day 14, further indicating the infection is being controlled." (PMID 31273203, 2019). "In addition to the cell migration, the infection of microglia with P. gingivalis significantly increased the mRNA expression of proinflammatory mediators, including IL-6, TNF-α, and iNOS, without affecting the mRNA expression of anti-inflammatory mediators, including IL-10, arginase-1 and IL-4." (PMID 28924232, 2017). "Additionally, infection did not upregulate splenic arg1 mRNA expression in mice." (PMID 22275864, 2012). "In addition, cytokines such as IL-4 produced during infection could mediate arginase-1 induction in infected and noninfected cells, and this could also complicate the results." (PMID 21931552, 2011). "We next infected mice with 50×106 RC to assess expression of AAM-associated molecules at both mRNA and protein levels at time points earlier than 48 hours p.i. to determine whether the expression of Arg1 but not NOS2 was evident from times very early after infection." (PMID 21246055, 2011). "M1-type markers (iNOS, CXCL-10, and CD86) were significantly upregulated after infection, and the expression level of M2-type markers (CD206 and ARG1) did not change significantly." (PMID 36352407, 2022). "While NRAMPG169 C57BL/6N BMDM contained lower numbers of intracellular Salmonella at 14 and 24 h after infection than C57BL/6N BMDM, blockade of ARG1 activity did not change the bacterial load." (PMID 34359992, 2021). "Our results showed that elevated expression and activity of ARG-1, but not ARG-2, were present in multiple cells post-infection, along with declined expression of T cell receptor CD3ζ chain in CD4+ and CD8+ T cells." (PMID 32029006, 2020). "Further, infection of BMM with E. muris, but not IOE, increased expression of arginase-1, a marker of M2 cells, as evidenced by immunoblotting analysis." (PMID 31575880, 2019). "The cytokines IL-12 and IL-4 induce CAT2B expression and the uptake of L-arginine, a substrate of ARG1 and NOS2, altering outcome of infection, while the negative regulation of CAT2B expression also reduces the infectivity of L. amazonensis." (PMID 30555476, 2018). "Expression of the gene coding for arginase (Arg1), an enzyme that competes with iNOS for using arginine as a substrate, was significantly repressed in STAT and VBNC conditions, with the same trend being observed for LOG infection although not significant." (PMID 38033163, 2023). "In contrast to the clear MyD88-dependence of these chemokines and IFNγ-response genes, the induction of the immunoregulatory cytokine IL-10 and of the enzyme Arginase-1 by NMII was largely independent of MyD88, which contrasts to the results obtained with BMM after infection with NMII in vitro." (PMID 30800124, 2019). "The present in vivo study shows for the first time that after infection with Mtb the absence of macrophage SOCS3 resulted in exacerbated alternative macrophage activation with strikingly increased levels of Fizz1, Ym1, Il4ra, and Arg1." (PMID 29176982, 2017).
infection (continued). "Of note, we could not detect any Arg1 expressing cells in the granuloma of 1° Hp infected C57BL/6 mice, indicating that effector mechanisms that arise only following challenge infection are required for Arg1 upregulation." (PMID 24244174, 2013).
inflammation (14 papers, 2013 to 2025). Aberrant reaction of the microcirculation characterized by movement of fluid and leukocytes from the blood into extravascular tissues. "MDSCs’ immunomodulatory function, linked to increased Arg-1 and iNOS expression, may be involved in exacerbated lung inflammation post-anti-IL10 treatment in our model." (PMID 37443161, 2023). "During autoimmune inflammation, Arg1 is upregulated in monocyte-derived cells due to their interaction with TNF-α activated blood–brain barrier cells." (PMID 37893243, 2023). "By contrast, alternatively activated macrophages are defined by tissue expression of Arg1 and other markers, such as Ym1, Fizz1, and the IL-4Rα-subunit especially during pulmonary inflammation." (PMID 29176982, 2017). "Mice that received Th2 cells secreted IL-4, IL-5 and IL-9 and up-regulated Arg1, Eotaxin (Ccl11) and Gob5 (Clca3) within the lung, characteristic of Th1 or Th2-mediated airway inflammation." (PMID 23825948, 2013). "Th2-driven lung inflammation increases Arginase 1 (Arg1) expression in alternatively-activated macrophages (AAMs)." (PMID 23637937, 2013). "Furthermore, we found that eliminating iNOS in combination with Arg1 also had little effect, suggesting that the Arg1-iNOS nexus in macrophages is dispensable for all obvious phenotypes of Th2-driven lung inflammation." (PMID 23637937, 2013). "Moreover, in a model of cerebral inflammation induced by the administration of hemine to primary cultures of microglia, lysine increased the levels of arginase-1 (Arg-1), CD206 (cluster of differentiation 206), and Ym1 which are markers of immune regulatory M2 macrophages." (PMID 34445459, 2021).
cardiovascular disease (13 papers, 2013 to 2025). "Inhibition of arginase-1 restores endothelial function and production of nitric oxide in studies of cardiovascular disease." (PMID 34341659, 2021). "Role of ARG1 in cardiovascular disease has been studied extensively, especially in the regulation of the immune system." (PMID 27672514, 2016). "In the present study, we found that prebiotic/probiotic supplementation reduced ARG1 (30 days), ATM (90 days), and CD80 (60 days), which may translate to a reduced cardiovascular disease risk." (PMID 36437471, 2022). "Furthermore, we proved that the maternal-smoking-induced ARG1 expression in Sm-RBCs may even augment the vascular dysfunction and serve as the etiology for cardiovascular diseases." (PMID 33918732, 2021).